IL6R (interleukin 6 receptor)
Diseases named in the same sentence as IL6R in open-access papers (continued):
Sharing a sentence is not in itself a finding about the gene and the disease.
pancreatic cancer (20 papers, 2015 to 2025). "Pancreatic cancer-educated macrophages upregulate CD59 expression on pancreatic cancer cell lines through STAT3 phosphorylation via the IL-6R/STAT3 signaling pathway and protect them from complement-dependent cytotoxicity." (PMID 40370471, 2025). "Here, we demonstrated a completely opposite outcome of IL-6 targeting, as impairing IL-6 signaling in the TME with an IL-6R blocking antibody abolished the antitumor activity of the TGFβ vaccine in a murine model of pancreatic cancer." (PMID 39653766, 2025). "Using flow cytometry, we validated myeloid cells and TAMs as the main IL-6R+ cell subsets in Pan02 cells, a murine model of pancreatic cancer." (PMID 39653766, 2025). "Mechanistically, SPON1 exerts its oncogenic roles in pancreatic cancer by maintaining IL‐6R trans‐signalling through stabilizing the interaction of soluble IL‐6R (sIL‐6R) and glycoprotein‐130 (gp130) in PDAC cells." (PMID 35487760, 2022). "Here, we suggest that pancreatic cancer-educated macrophages induce the upregulation of CD59 in an IL-6R/STAT3-dependent manner in pancreatic cancer cells." (PMID 31685825, 2019). "In summary, crosstalk between macrophages and pancreatic cancer cells through the upregulation of CD59 in an IL-6R/STAT3 manner protects pancreatic cancer from CDC." (PMID 31685825, 2019). "In a study using an orthotopic xenograft model with pancreatic cancer cells, treatment with Tocilizumab (anti-IL-6R) resulted in a remarkable decrease in tumor weight and new metastases compared to a control group." (PMID 30038723, 2018). "The use of IL-6 as a therapeutic target is currently being investigated for pancreatic cancer, but trials should be done for the three other cancers types, especially since inhibition of anti-IL-6R with Tocilizumab seems to be well tolerated." (PMID 30038723, 2018). "To discern the cellular subsets susceptible to IL-6R blockade that could compromise the responsiveness to immune checkpoint inhibition and radiotherapy, we assessed the expression of IL6R in human pancreatic tumors." (PMID 39653766, 2025). "Given the elevated expression of IL-6R in myeloid cells in pancreatic tumors, we hypothesized that myeloid cells, specifically macrophages, could be notably affected by IL-6R blockade." (PMID 39653766, 2025). "Preclinical studies document improved response to chemotherapy in mice with pancreatic cancer treated with anti-IL6R antibodies; whether these mice also demonstrated reduced cachexia was not reported." (PMID 33851955, 2021). "Therapeutics targeting FOXO signaling pathways and IL6-R are in various stages of testing in pancreas cancer, but whether these might have beneficial impact on cachexia needs to be investigated." (PMID 33923976, 2021). "To test our hypothesis that IL-6 is responsible for the activation of the STAT3 pathway in pancreatic cancer cells, we performed experiments where we neutralized the IL-6 receptors (IL-6Rs) using the IL-6R neutralizing monoclonal antibody Tocilizumab." (PMID 34440697, 2021). "Pancreatic cancer-educated macrophages could protect cancer cells from CDC by up-regulating CD59 via the IL-6R/STAT3 signaling pathway." (PMID 31685825, 2019). "In patients with pancreatic cancer, treatment with anti-IL-6R could potentially result in an amelioration of the severe symptoms from which many patients with metastatic pancreatic cancer suffer." (PMID 30038723, 2018). "Preclinical studies have demonstrated that treatment with anti-IL-6 or anti-IL-6R blocking antibodies can increase the efficacy of immunotherapy, reduce tumor progression, and increase T-cell infiltration in several murine tumor models, including those of pancreatic cancer." (PMID 39653766, 2025). "While combining immune checkpoint inhibitors (ICIs) and radiotherapy in patients with pancreatic cancer (PC) has yielded promising clinical results, the addition of an anti-IL-6 receptor (IL-6R) antibody has failed to elicit clinical benefits." (PMID 39653766, 2025).
pancreatic cancer (continued). "Thus, in vitro blocking of IL-6R signaling by TCZ showed pSTAT3 downregulation and inhibition of IL-6 expression in both pancreatic cancer cells and mesenchymal stem cells (MSCs)." (PMID 38715108, 2024). "CD59 has been reported to be highly expressed in patients with pancreatic cancer, and Pancreatic cancer-educated macrophages could up-regulate CD59 to protect cancer cells from CDC through the IL-6R/STAT3 signaling pathway." (PMID 35237592, 2022). "Unexpectedly, no clinical responses were observed, suggesting that IL-6R blockade might have affected the beneficial effects of combining checkpoint inhibition with radiotherapy in patients with pancreatic cancer." (PMID 39653766, 2025). "However, tocilizumab, a humanized monoclonal antibody against the IL-6R, in combination with cytotoxic chemotherapy in patients with advanced pancreatic cancer did not demonstrate an improvement in survival outcomes." (PMID 38672257, 2024). "In this study, we observed that pancreatic cancer cells could induce macrophages to exhibit a tumor-promoting phenotype, and then the tumor-promoting macrophages induced CD59 expression in cancer cells by IL-6 secretion and by inducing IL-6R expression in cancer cells." (PMID 31685825, 2019). "In this study, the cytokine‒cytokine receptor interaction pathway was the most enriched pathway between pancreatic cancer cells treated with and without glutamine, includingCCL5,CCR4,LTA,CXCR4,IL-6R, andIL-7R." (PMID 36942991, 2023).
Crohn disease (19 papers, 2004 to 2024). A gastrointestinal disorder characterized by chronic inflammation involving all layers of the intestinal wall, noncaseating granulomas affecting the intestinal wall and regional lymph nodes, and transmural fibrosis. "Third, our study can only suggest a causal association between Crohn’s disease, IL-6 and IL-6R and alterations in cerebral cortical structures." (PMID 37153572, 2023). "We confirmed that genetic liability to Crohn’s Disease and high IL-6/IL-6Rα levels were causally associated with alterations in TH or SA in some brain regions, which further corroborated the organoleptic connection of the gut-brain axis." (PMID 37153572, 2023). "We used the effect of rs2228145 on s-IL6R level as an indirect marker to investigate whether reduced IL6R signaling associates with risk of ulcerative colitis (UC) or Crohn’s disease (CD)." (PMID 29775600, 2018). "A pilot phase II study using the neutralising anti-IL-6R antibody tocilizumab suggested a clinical response in Crohn’s disease (CD) patients, and several inhibitors of the IL-6 pathway are in clinical development, some also for IBD." (PMID 29748708, 2018). "Tocilizumab, a humanized monoclonal anti-IL-6R antibody that is an FDA-approved drug for rheumatic arthritis and Crohn’s disease, competitively binds to both soluble and membrane-bound IL-6 receptors and blocks the intracellular IL-6 signaling pathway." (PMID 30927911, 2019). "In a small, pilot clinical study, treatment of patients with active Crohn's disease with a humanized monoclonal antibody to IL-6R significantly improved disease activity scores but did not improve endoscopic and histologic scores." (PMID 25478789, 2014).
glioma (19 papers, 2014 to 2025). A benign or malignant brain and spinal cord tumor that arises from glial cells (astrocytes, oligodendrocytes, ependymal cells). "As shown by soft-agar colony formation, loss of IL6R expression significantly decreased glioma cells tumorigenesis in vitro 1.5–1.8-fold." (PMID 29258522, 2017). "Interestingly, high expression levels of IL‐6 and IL‐6R have been associated with aggressive subtypes of glioma (i.e. mesenchymal subtype and IDH wild‐type glioma)." (PMID 35029050, 2022). "In support, in vitro blocking of IL-6R inhibits cell proliferation, invasion, and neuroglobular formation of glioma tumors." (PMID 38715108, 2024). "Specifically, the covalent decoration of superparamagnetic iron oxide with interleukin-6 receptor-targeting peptide allows the particle to pass through the blood brain barrier, making it useful for the identification of low-grade glioma." (PMID 37214394, 2023). "IHC staining showed that both IL-18R and IL-6R protein levels were down-regulated by MAP4K1-KD in mouse subcutaneous glioma tissues constructed with U87 cells compared with those in NC groups." (PMID 37734869, 2023). "Correlation analysis from different CGGA datasets (batch 2 and batch 1) showed a positive correlation of MAP4K1 with either IL-18R or IL-6R mRNA levels in human gliomas." (PMID 37734869, 2023). "IL6R expression has been shown as a predictor of poor survival in glioma effecting tumor progression." (PMID 31952211, 2020). "To evaluate the functional significance of IL6R upregulation in gliomas, we knocked-down the expression of IL6R in M1 cells and U87 cells, both of which normally have high IL6R expression levels, using two specific shRNAs." (PMID 29258522, 2017). "IL6R knockdown significantly inhibited the tumourigenesis of glioma cells both in vitro and in vivo." (PMID 29258522, 2017). "To further confirm the role of IL6R in glioma growth and invasion, we overexpressed IL6R in N2 cells with low levels IL6R." (PMID 29258522, 2017). "For example, interleukin 6 (IL-6)/IL-6 receptor (IL-6R)-mediated signaling pathways are involved in the regulation of EMT in glioma cells." (PMID 27524415, 2017). "Compared with the classical, neural, and proneural glioma cells, the levels of IL6 and IL6R mRNA and protein expression were higher in mesenchymal glioma cells." (PMID 29258522, 2017). "High IL6- and IL6R-expression were significantly associated with mesenchymal subtype and IDH-wildtype gliomas, and were predictors of poor survival." (PMID 29258522, 2017). "To determine the role of IL6R in glioma tumourigenesis in vivo, we separately implanted M1-control-shRNA, M1-IL6R-shRNA1, M1-IL6R-shRNA2, N2-EV-control or N2-IL6R-OE cells into the brains of mice." (PMID 29258522, 2017). "We found that the levels of IL6 and IL6R expression were significantly higher in mesenchymal subtypes of glioma compared with classical, neural, and proneural subtypes, respectively." (PMID 29258522, 2017). "IL6R knockdown also inhibited glioma cell invasion 2.2–3.1-fold and migration 1.5–2.4-fold." (PMID 29258522, 2017). "Next, we examined the expression of IL6 and IL6R in patient-derived primary glioma cells." (PMID 29258522, 2017). "Importantly, we found that IL6-stimulated glioma growth and invasion was largely dependent on the expression of IL6R." (PMID 29258522, 2017). "Therefore, in the present study, we examined the role of IL6 and IL6R along with their regulatory factors in gliomas." (PMID 29258522, 2017). "We first examined IL6 and IL6R mRNA expression in clinical gliomas using TCGA dataset." (PMID 29258522, 2017). "In addition, upregulation of both IL6 and IL6R was associated with decreased survival rates in both TCGA and REMBRANDT gliomas." (PMID 29258522, 2017).
glioma (continued). "The strong association between IDH-wildtype gliomas and upregulation of IL6 and IL6R expression suggests that the IL6 signalling may contribute to the poor prognosis of patients with wild-type IDH1, although the exact mechanism requires further research." (PMID 29258522, 2017). "Moreover, compared with the IDH-mutant gliomas, the levels of IL6 and IL6R mRNA expression were higher in IDH-wildtype gliomas." (PMID 29258522, 2017). "Targeting IL-6R or IL-6 ligand gp130 expression in glioma stem cells with a shRNA significantly reduced growth and neurosphere formation capacity, at the same time increased the apoptosis in GSCs culture and survival of mice bearing intracranial human glioma xenografts." (PMID 28927416, 2017). "Therefore, IL6R of the tumour cells might be a better target than IL6 for the potential novel treatment of gliomas." (PMID 29258522, 2017). "Functionally, OSMR - a leukocyte interleukin-6 receptor- activates JAK-STAT3 signaling upon binding oncostatin M (OSM), thereby driving glioma proliferation, invasion, and apoptosis resistance." (PMID 40859405, 2025). "In the present study, using TCGA database and patient-derived primary glioma cells, we found both IL6 and IL6R expression were significantly correlated with mesenchymal subtype and IDH-wildtype gliomas, and were predictors for unfavourable prognosis." (PMID 29258522, 2017). "In glioma cells, NFAT1 enhanced the promoter activities of IL6R and IL6, and upregulated the expression of both IL6R and IL6." (PMID 29258522, 2017). "IL6R overexpression or IL6 stimulation enhanced the invasion and growth of glioma cells." (PMID 29258522, 2017). "In gliomas, the NFAT1/IL6/IL6R pathway may mediate crosstalk between tumours and immune cells resulting in a tumour-promoting inflammatory microenvironment." (PMID 29258522, 2017). "In addition to these, MAPKAPK2 is positively correlated with IL6, IL6R, IL10, IL10RB, TGFβ1, etc., in the present study, which may facilitate the glioma progression." (PMID 38322416, 2024).
inflammatory bowel disease (18 papers, 2014 to 2024). A spectrum of small and large bowel inflammatory diseases of unknown etiology. "MR analyses supported a causal role for IL-18 in inflammatory bowel disease (IBD) (P = 1.17 × 10−4) and eczema/dermatitis (P = 2.81 × 10−3), as well as associations between IL-2rα and IL-6R with several other IMDs." (PMID 31276585, 2019). "In patients with inflammatory bowel disease, treatment with the IL-6R neutralizing antibody Tocilizumab suggested a clinical benefit, but this treatment has not been approved by the FDA." (PMID 31694340, 2019). "Interleukin 6 (IL6) is an inflammatory cytokine; signaling via its receptor (IL6R) is believed to contribute to development of inflammatory bowel diseases (IBD)." (PMID 29775600, 2018). "Whether interleukin-6 receptor (IL6R) blockade reduces the risk of developing inflammatory bowel disease (IBD) is unknown." (PMID 29775600, 2018). "Similarly, in type 1 diabetes and inflammatory bowel disease, despite the role of IL6R in immune modulation, the effects of IL6Ri are likely moderated by other significant genetic or environmental factors, reducing its singular impact." (PMID 39229261, 2024). "Interleukin-6 receptor (IL-6R), stimulated by IL-6, triggers intricate cell functions including immune cell activation, hematopoietic stem cell differentiation, cancers, and inflammatory bowel diseases." (PMID 38256960, 2024). "At the global level, neither inflammatory bowel diseases nor inflammatory cytokines (IL-6 and IL-6Rα) have been found to be causally associated with brain cortex structures." (PMID 37153572, 2023). "Correspondingly, the inhibition of IL-6 transsignaling, wherein the complex of IL-6 and sIL-6R can stimulate cells that do not express IL-6R (such as endothelial cells and smooth muscle cells), is sufficient to block disease in mouse models of inflammatory bowel disease and RA." (PMID 34156295, 2021).
myocardial infarction (18 papers, 2012 to 2026). Gross necrosis of the myocardium, as a result of interruption of the blood supply to the area, as in coronary thrombosis. "Treatment with anti-inflammatory drugs such as tocilizumab, an interleukin-6 receptor antagonist, has been shown to reduce troponin release and reduce the myocardial infarct size in AMI patients and it may therefore have cardioprotective properties." (PMID 39501388, 2024). "The objectives of the present study were to further explore IL-6 signalling during acute myocardial infarction (MI) by studying the potential role of acute and sustained IL-6 and soluble IL-6R elevation up to 4 months post-MI." (PMID 34933964, 2021). "An ongoing clinical trial by the same investigators is assessing the effect of anti-IL-6R treatment with tocilizumab in the setting of a ST-segment elevation myocardial infarction (ASSAIL-MI trial; NCT03004703)." (PMID 31672136, 2019). "To disentangle the association of IL6R with inflammation and risk of CHD, we analyzed the association of IL6R haplotypes with circulating levels of inflammatory biomarkers [CRP, fibrinogen, sIL6R, IL6, interleukin 8 (IL8) and TNF-α] and with the risk of myocardial infarction (MI) and CHD." (PMID 25781951, 2015). "A randomized, placebo-controlled trial, ASSessing the effect of Anti-IL-6 treatment in Myocardial Infarction (ASSAIL-MI), demonstrated that IL-6R inhibition with tocilizumab administered during PCI in patients with STEMI reduced the inflammatory response and myocardial damage." (PMID 40508157, 2025).
Stroke (18 papers, 2014 to 2026). Sudden impairment of blood flow to a part of the brain due to occlusion or rupture of an artery to the brain. "To the best of our knowledge, this is the first time we revealed that carriers of the IL6R rs4845625 TT genotype was associated with an increased risk of vulnerable carotid plaque in Chinese Han high-risk individuals for stroke in a sex-specific manner." (PMID 36060677, 2022). "We have provided statistical evidence that the rs4845625 polymorphism in IL6R has sex-specific effects on vulnerable carotid plaque in Chinese Han high-risk individuals for stroke." (PMID 36060677, 2022). "Similarly, a large genome-wide association study has confirmed the relationship of the Interleukin-6 receptor with all stroke events, except for those due to cardioembolism." (PMID 40472800, 2025). "Our findings indicate that the upregulation of Ptgs2, Lgals3, Il6r, and Jak3 further enhances the inflammatory response following stroke." (PMID 39847586, 2025). "Our study demonstrated that MSTRG.151823.1 modulates the expression of multiple apoptosis-related genes, including Bag3, Serpine1, and Il6r, following stroke." (PMID 39847586, 2025). "We prospectively studied a cohort of 3396 stroke patients with identified etiologies, and identified CHIP and the presence of the IL6R variant (IL6R p.Asp358Ala) by whole-genome sequencing." (PMID 38104193, 2023). "Post-stroke angiogenesis resembles in many ways the angiogenesis in tumors, i.e., the newly formed vessels are leaky via the Il6r/Il6st/STAT1/3 pathway." (PMID 24672479, 2014). "We tested whether inhibition of IL-6 signaling with the IL-6 receptor (IL-6R) blocking antibody tocilizumab (TCZ) improves recovery after experimental stroke." (PMID 42146493, 2026). "Notably, stroke patients exhibited an inverse relationship between miR-21-5p and IL-6R in their peripheral blood, with miR-21-5p levels being significantly decreased." (PMID 40981170, 2025). "By introducing miR-21-5p (or blocking IL-6R) in cellular models of stroke, researchers could alleviate inflammation-induced damage." (PMID 40981170, 2025). "Stroke showed a somewhat different profile of associations, with evidence for causal effect for thrombotic risk factors (factor VII, factor XI, platelet count, vitamin K), iron and inflammatory biomarkers (iron, transferrin, transferrin saturation, IL6R), and blood pressure." (PMID 37804188, 2023).
atrial fibrillation (17 papers, 2013 to 2026). A disorder characterized by an electrocardiographic finding of a supraventricular arrhythmia characterized by the replacement of consistent P waves by rapid oscillations or fibrillatory waves that vary in size, shape and timing and are accompanied by an irregular ventricular response. "Recent studies have identified a variant, rs4845625, in the interleukin-6 receptor (IL6R) gene associated with Atrial Fibrillation (AF)." (PMID 24940886, 2014). "Three out of the four proteins (DUSP13, TNFSF12 and IL6R) had a drug prioritizing score for atrial fibrillation of 0.26, 0.38 and 0.88, respectively (values closer to 1 indicating stronger evidence of the protein as a potential drug target)." (PMID 35292824, 2022). "We also identified two SNVs in the intronic regions of IL6R, rs4129267, and rs12126142, to be shared by AAA with atrial fibrillation and CAD, respectively." (PMID 38969659, 2024).